ARHGEF19 (Rho guanine nucleotide exchange factor 19)
Description:
Acts as a guanine nucleotide exchange factor (GEF) for RhoA GTPase.
Synonyms: FLJ33962; WGEF
Tractability: PROTAC: ubiquitination databases record sites on it.
Gene: Protein-coding gene on chromosome 1 (16,197,854 to 16,212,893, reverse strand). Ensembl gene ENSG00000142632.
Subcellular location (Human Protein Atlas): Nuclear bodies
Pathways (Reactome):
Signal Transduction: CDC42 GTPase cycle; G alpha (12/13) signalling events; NRAGE signals death through JNK; RAC1 GTPase cycle; RHOA GTPase cycle
Gene Ontology:
Molecular function: protein binding; guanyl-nucleotide exchange factor activity
Biological process: regulation of actin cytoskeleton organization; regulation of small GTPase mediated signal transduction; Wnt signaling pathway, planar cell polarity pathway; wound healing
Cellular component: cytosol
Genetic constraint (gnomAD): Loss-of-function variants: 95 observed, 84.93 expected, observed/expected ratio (o/e) 1.12, 90% interval 0.95 to 1.33. The upper end of that interval is the gene's LOEUF score, 1.33, which puts it in group 5 of 6, group 1 being the genes least tolerant of losing a copy. Missense variants: 1,054 observed, 1,009.4 expected, observed/expected ratio (o/e) 1.04, 90% interval 0.99 to 1.1. Synonymous variants: 438 observed, 425 expected, observed/expected ratio (o/e) 1.03, 90% interval 0.95 to 1.12.
Homologues: Orthologues: chimpanzee ARHGEF19 (99% identical), macaque ARHGEF19 (97% identical), pig ARHGEF19 (92% identical), dog ARHGEF19 (90% identical), rat Arhgef19 (85% identical), mouse Arhgef19 (85% identical), rabbit ARHGEF19 (67% identical), zebrafish arhgef19 (53% identical), tropical clawed frog arhgef19 (35% identical), Caenorhabditis elegans ephx-1 (26% identical). Paralogues in human: ARHGEF5 (41% identical), NGEF (28% identical), ARHGEF15 (25% identical), ARHGEF26 (24% identical), ARHGEF16 (22% identical), ARHGEF35 (11% identical).
Diseases named in the same sentence as ARHGEF19 in open-access papers:
ARHGEF19 is named in the same sentence as 12 diseases in open-access papers, as found by Europe PMC text mining. Sharing a sentence is not in itself a finding about the gene and the disease. The quoted sentences say what the papers report.
Intellectual disability (2 papers, 2018 to 2022). "Specific RhoGEFs have been implicated in neurodevelopmental disorders, such as language impairment (ARHGEF19), intellectual disability (ARHGEF6, ARHGEF2), and moderate intellectual disability with speech delay (ARHGEF9)." (PMID 35959104, 2022).
cleft lip (1 paper, 2025). Congenital defect in the upper lip where the maxillary prominence fails to merge with the merged medial nasal prominences. "After clumping, we identified 18 regions (2 mapping to ARHGEF18 (19p13.2) and ARHGEF19 (1p36.13) were novel) which showed the smallest p-values in the cleft lip with or without cleft palate (CL/P) or nsCL/P subtype GWAS and which were associated with both CLO and CLP." (PMID 41075272, 2025).
endometriosis (1 paper, 2024). The growth of functional endometrial tissue in anatomic sites outside the uterine body. "Arhgef19, a gene implicated in signaling pathways related to cell migration and cytoskeleton organization, was elevated in mouse endometriosis-like lesions compared to decidual tissue, while ARHGEF19 is downregulated in peritoneal endometriosis lesions in human." (PMID 39385609, 2024).
lung carcinoma (1 paper, 2020). "ARHGEF19 is a RhoGEF that reportedly activates the MAPK pathway and interacts with BRAF in lung cancer." (PMID 33322675, 2020).
cancer (3 papers, 2019 to 2021). A tumor composed of atypical neoplastic, often pleomorphic cells that invade other tissues. "All target genes except ARHGEF19 were upregulated in cancer tissues in this cohort." (PMID 33322675, 2020).
tumor (2 papers, 2024 to 2025). "Six genes—ARHGEF19, CORO1A, ACOT7, ZC3H18, SLC5A5, and ZFAS1—showed statistically significant differential expression between tumor and normal tissues (P < 0.05)." (PMID 40070828, 2025).
lip (1 paper, 2025). "Novel loci include those mapping to LHX8 and TSBP1 (combined clefts), ARHGEF18 and ARHGEF19 (cleft lip with/without palate), FBN2 (cleft lip only), SLC35B3 (cleft palate only), CASC20 (Pierre Robin Sequence) and CHRM2 (non-syndromic cleft palate only)." (PMID 41075272, 2025).
ARHGEF19 also shares sentences with these, for which no sentence is quoted: cleft palate (1 paper); hepatocellular carcinoma (1); non-small cell lung carcinoma (1); speech delay (1); urothelial carcinoma (1).